BCAR4 (breast cancer anti-estrogen resistance 4)
Diseases named in the same sentence as BCAR4 in open-access papers (continued):
Sharing a sentence is not in itself a finding about the gene and the disease.
breast cancer (continued). "Here, we showed that a lncRNA, Breast-Cancer Anti-Estrogen Resistance 4 (BCAR4), which plays a pivotal role in the tamoxifen-resistance of breast cancer, was significantly upregulated in CRPC, but not in castration-sensitive prostate cancer (CSPC), compared to normal prostate tissue." (PMID 30513511, 2018). "Furthermore, it has been proved that BCAR4 can promote breast cancer cell migration and invasion through noncanonical hedgehog signaling pathway." (PMID 30026672, 2018). "Moreover, YAP could upregulate BCAR4 expression and coordinate the Hedgehog signalling pathway to promote the transcription of glycolysis activators HK2 and PFKFB3, and in turn to reprogramme glucose metabolism in breast cancer." (PMID 32779318, 2020). "BCAR4, thus enhances transcription of GLI-2 dependent target genes in breast cancer cells through a non-canonical hedgehog-GLI pathway." (PMID 29732012, 2018).
osteosarcoma (11 papers, 2017 to 2025). A usually aggressive malignant bone-forming mesenchymal neoplasm, predominantly affecting adolescents and young adults. "miR-1260a levels are elevated in osteosarcoma tissues, but its expression is in opposition to BCAR4, depicting the direct interplay between BCAR4 and miR-1260a." (PMID 40868849, 2025). "After knocking down BCAR4, the proliferation, invasion and migration of osteosarcoma cells were inhibited." (PMID 39015175, 2024). "The lncRNA Breast cancer anti-estrogen resistance 4 (BCAR4) has both prognostic and therapeutic significance in osteosarcoma." (PMID 29657304, 2018). "Mechanistically, BCAR4 promotes osteosarcoma cell metastasis by activating the GLI2-dependent pathway." (PMID 28353666, 2017). "In addition, BCAR4 promotes the progression of osteosarcoma by activating the GLI2 signaling pathway." (PMID 39015175, 2024). "LncRNA BCAR4 overexpression was correlated with unfavorable OS in patients with osteosarcoma (HR 2.57, 95% CI: 1.53–4.32; P < .001, I2 = 0%), digestive system cancer (HR 2.89, 95% CI: 1.84–4.54; P < .001, I2 = 0%), and other system malignancies (HR 3.00, 95% CI: 1.61–5.60; P < .001, I2 = 0%)." (PMID 31124974, 2019). "BCAR4 was significantly upregulated in human osteosarcoma tissue." (PMID 28353666, 2017). "Knockdown of BCAR4 inhibited the metastasis of human osteosarcoma cell lines in vitro and in vivo." (PMID 28353666, 2017). "Consequently, BCAR4 could serve as a therapeutic target in the treatment of osteosarcoma, as this would inactivate the GLI2 pathway and GLI2-dependent target genes." (PMID 29657304, 2018). "For example, nine lncRNAs (91H, FGFR3-AS1, BCAR4, TUG1, UCA1, HIF2PUT, HOTTIP, HULC, and MALAT-1) are up-regulated in osteosarcoma, which is considered oncogenic for osteosarcoma." (PMID 31850493, 2020). "On the other hand, knockdown of BCAR4 in-vitro using cell lines MG63 and U2-OS inhibits osteosarcoma cell proliferation and migration by inhibiting the transcription of GLI family zinc finger 2 (GLI2)-dependent target genes." (PMID 29657304, 2018). "Nine different long non-coding RNAs were studied in these 10 included articles, with 7 lncRNAs including MALAT1, BCAR4, FGFR3-AS1, HOTAIR, TUG1, FOXC2-AS1 and PVT1 were up-regulated in osteosarcoma cells or patients." (PMID 29245999, 2017). "BCAR4 promotes proliferation and migration of osteosarcoma cells by regulating the nonclassical Hedgehog/GLI2 signaling pathway." (PMID 34048366, 2021). "In addition, several other lncRNAs, including BCAR4, FGFR3-AS1, HNF1A-AS1 and ZEB1-AS1 were highly expressed in human osteosarcoma patients and correlated with poor prognosis." (PMID 28353666, 2017).
cervical cancer (7 papers, 2017 to 2024). A primary or metastatic malignant neoplasm involving the cervix. "The Cancer Genome Atlas (TCGA) research network reported the first fusion events in cancer involving the BCAR4 gene in cervical cancer and suggested lapatinib as a possible therapeutic option." (PMID 38919532, 2024). "BCAR4 expression promoted the proliferation and motility of cervical cancer cells by enhancing epithelial–mesenchymal transition (EMT)." (PMID 36081848, 2022). "In the TCGA, ZC3H7A-BCAR4 was the most frequently detected fusion gene in cervical cancer, accompanied by amplifications of BCAR4." (PMID 33398034, 2021). "Another prospective therapeutic target is BCAR4, in which amplifications and gene fusions have been found in cervical cancer and which is targeted by lapatinib." (PMID 28771191, 2017). "Overexpressed BCAR4 has been reported in cervical cancer, non-small cell lung cancer (NSCLC), and gastric cancer, suggesting that it may be a biomarker for poor prognosis." (PMID 36081848, 2022). "Besides, the overexpression of BCAR4 may be an independent prognostic factor of cervical cancer, and it can promote the proliferation and movement of cervical cancer cells." (PMID 32883200, 2020).
gastric cancer (7 papers, 2019 to 2024). A primary or metastatic malignant neoplasm involving the stomach. "Onco-lncRNAs zinc finger antisense 1 (ZFAS1) and BCAR4 could promote DDP resistance of gastric cancer via activating the Wnt signaling pathway." (PMID 32192494, 2020). "Further studies have shown that BCAR4 activates the Wnt/β-catenin signaling pathway and up-regulates the expression of stemness markers nanog, OCT3/4, SOX2, c-Myc, and KLF4, which further enhance gastric cancer cell stemness and DDP resistance." (PMID 32460771, 2020).
bladder cancer (6 papers, 2018 to 2023). "Subsequent investigations have shown that BCAR4 functions as a promoter for various human malignancies, including bladder cancer." (PMID 36605618, 2023). "This is the first study to show that BCAR4 and miR-644a can regulate the expression of TLX1 and the expression of TLX1 was associated with bladder cancer progression." (PMID 37627900, 2023). "For example, BCAR4 aggravates bladder cancer development via functioning as a miR-370-3p sponge to activate Wnt signaling pathway." (PMID 33088221, 2020). "BCAR4 promoted the cell proliferation, migration, and invasion of bladder cancer." (PMID 37627900, 2023). "Three lncRNAs, including LNMAT1, CTD-2231H16.1 and BCAR4, were consistently upregulated in both the MIBC and LN-positive bladder cancer tissues." (PMID 30237493, 2018).
colorectal cancer (6 papers, 2017 to 2022). A primary or metastatic malignant neoplasm that affects the colon or rectum. "Consistently, compared to normal colon epithelial cells (CCD 841 CoN), colorectal cancer cells exhibited high level of BCAR4." (PMID 30962766, 2019). "In this study, owing to the heterogeneity of colon cancer, we first examined the expression of BCAR4 in colorectal cancer tissues." (PMID 30962766, 2019). "LncRNA BCAR4 maintains colorectal cancer cell stemness by targeting the miR-665/STAT3 pathway." (PMID 34349799, 2021). "Previous studies reported that BCAR4 was highly expressed in colon cancers, however, the detailed mechanisms of BCAR4 functioned in colorectal cancer cells remains unclear." (PMID 30962766, 2019). "In addition, immortalized colon cancer cell lines, such as HCT-116, SW480 and HCT8, were applicable to confirm the pivotal role of BCAR4 in colorectal cancer." (PMID 30962766, 2019). "In this study, we found that BCAR4 was highly expressed in the colorectal cancer tissues." (PMID 30962766, 2019). "To in-depth study the function of BCAR4 in CSCs, we constructed the stable colorectal cancer cells (HCT-116-pBABE-puro-BCAR4 and HCT-8-pLKO.1-BCAR4) with BCAR4 over-expression or inhibition." (PMID 30962766, 2019). "Additionally, the stemness of cancer cells in colorectal cancer can be regulated by lncRNA FARAS1, LINC00657, HOTAIR, and BCAR4." (PMID 35470736, 2022). "Consequently, colorectal cancer cells (HCT116 and HCT8) with BCAR4 overexpression or inhibition were established to examine its function." (PMID 30962766, 2019).
non-small cell lung carcinoma (6 papers, 2017 to 2022). A group of at least three distinct histological types of lung cancer, including non-small cell squamous cell carcinoma, adenocarcinoma, and large cell carcinoma. "Upregulation of lncRNA BCAR4 accelerates the malignant development of non-small cell lung cancer, indicating BCAR4 might serve as a potential biomarker for non-small cell lung cancer treatment." (PMID 32351327, 2020). "Additionally, upregulated expression of BCAR4 is positively correlated with poor prognosis in patients with non-small cell lung cancer." (PMID 29190958, 2017).
colon cancer (5 papers, 2017 to 2023). "A third mechanism was reported in colon cancer: BCAR4 transcript can bind to and stabilize beta-catenin to activate canonical Wnt/beta-catenin signalling." (PMID 32193429, 2020). "Sphere formation assay revealed that colon cancer cells with higher expression of BCAR4 occupied stronger capacity of self-renewal." (PMID 30962766, 2019). "However, the mechanisms underlying BCAR4 function in colon cancer remains largely unknown." (PMID 30962766, 2019). "More importantly, results also showed the expression of BCAR4 in ALDH+ colon cancer cells (from both SW480 and HCT8) was significantly higher than ALDH− cells." (PMID 30962766, 2019). "Summarily, BCAR4 was upregulated in colon cancer and positively correlated with clinical severity and poor prognosis." (PMID 29190958, 2017). "In our study, we find for the first time that BCAR4 is a key factor in colon cancer cell proliferation and migration." (PMID 29190958, 2017). "In consistent with the observations above, overexpressing BCAR4 made more cells enter into cell cycle as shown by BrdU incorporation assays, suggesting that BCAR4 promotes cell proliferation in colon cancer." (PMID 29190958, 2017). "Our finding shows that BCAR4 is highly expressed in colon cancer and regulates cell proliferation and migration." (PMID 29190958, 2017). "To further confirm the relationship between BCAR4 and Wnt/β-catenin signaling, we detected the expression levels of BCAR4 and target genes of Wnt/β-catenin signaling by RT-qPCR in 30 colon cancer tissues." (PMID 29190958, 2017). "Then we evaluated the expression level of BCAR4 by Northern blot and RNA hybridization in situ, and found that more BCAR4 existed in colon cancer tissues than in adjacent normal tissues." (PMID 29190958, 2017). "Then we divided 60 colon cancer samples into two groups based on BCAR4's expression levels and analyzed the overall survival rate and disease-free survival rate." (PMID 29190958, 2017). "We found that overexpressing BCAR4 decreased the degradation of β-catenin in colon cancer samples while knocking down BCAR4 increased the instability of β-catenin." (PMID 29190958, 2017). "What's more, higher BCAR4 expression was correlated with lower survival rate in patients with colon cancer." (PMID 29190958, 2017). "In this study, we revealed that the expression levels of BCAR4 were upregulated in colon cancer tissues compared to adjacent normal tissues." (PMID 29190958, 2017). "Overexpressing BCAR4 in colon cancer cell line HCT8 and SW480 promotes cell proliferation and migration while BCAR4-silenced cells showed enhanced apoptosis and impaired proliferation." (PMID 29190958, 2017). "To determine how BCAR4 regulates colon cancer cells, we constructed BCAR4 overexpressing plasmid by cloning BCAR4 full-length into PCDNA3 vector." (PMID 29190958, 2017). "To further validate that the interaction of BCAR4 with β-catenin is essential for the proliferation of colon cancer cells, we explored the interactive region in BCAR4 by RNA pulldown assays." (PMID 29190958, 2017). "In our research, we found that the expression level of BCAR4 was upregulated in colon cancer tissues compared to paired normal tissues." (PMID 29190958, 2017). "Mechanistically, we showed that BCAR4 activated Wnt/β-catenin signaling in colon cancer by protecting β-catenin from degradation." (PMID 29190958, 2017). "In this study, we hypothesized that BCAR4 could regulate colon cancer stem/initiating cells (CSC) function and further facilitates the colon cancer progression." (PMID 30962766, 2019). "To further define the role of BCAR4 in colon cancer, we knocked down BCAR4 in HCT8 and SW480 cells." (PMID 29190958, 2017). "To validate that whether BCAR4 promotes colon cancer cell proliferation by Wnt/β-catenin signaling, we first examined the interaction between BCAR4 and β-catenin by RNA pulldown and RNA IP assays." (PMID 29190958, 2017).
colon cancer (continued). "To understand the role of BCAR4 in colon cancer, we analyzed its expression patterns." (PMID 29190958, 2017). "We also showed that BCAR4 overexpression promoted cell proliferation and migration in colon cancer." (PMID 29190958, 2017). "Collectively, our results reveal a new function of BCAR4 in colon cancer and may provide a new sight on treatment of patients with colon cancer." (PMID 29190958, 2017). "Moreover, BCAR4 was expressed higher in colon cancer cell lines such as HCT8, SW480 and HCT116 cells relative to normal human colon epithelial cell CCD 841 CoN." (PMID 29190958, 2017). "We show that BCAR4 was upregulated in colon cancer tissues compared to adjacent normal tissues." (PMID 29190958, 2017). "Collectively, BCAR4 promotes the proliferation and migration of colon cancer cells." (PMID 29190958, 2017). "BCAR4 expression was correlated with clinical severity and prognosis in colon cancer." (PMID 29190958, 2017). "In addition, BCAR4-miR-665-STAT3 ceRNA network might also function and could be a diagnostic marker of CRC as well as provided a therapeutic target in colon cancer treatment." (PMID 30962766, 2019). "To explore the mechanism by which BCAR4 regulates colon cancer cell, we analyzed the changes of some tumor-related signaling pathways including NK-κB signaling pathway, Notch signaling pathway, Hedgehog signaling pathway and Wnt/β-catenin signaling pathway after silencing BCAR4." (PMID 29190958, 2017). "Additionally, β-catenin can enrich BCAR4 in colon cancer samples." (PMID 29190958, 2017). "BCAR4 may act as a potential biomarker for diagnosis of colon cancer." (PMID 29190958, 2017). "And BCAR4 may serve as a new target for treatment of patients with colon cancer." (PMID 29190958, 2017). "BCAR4 may be a useful new target for treatment of patients with colon cancer." (PMID 29190958, 2017). "To further confirm that miR-665 was negatively regulated by BCAR4, we constructed the stable ALDH+ colon cancer cells with BCAR4 inhibition." (PMID 30962766, 2019). "Given the important role of BCAR4 in CRC, we intended to find the target genes of BCAR4 in colon cancer." (PMID 30962766, 2019). "Therefore, we hypothesized that whether BCAR4 could regulated CSCs in colon cancer." (PMID 30962766, 2019). "Evidence so far suggested that BCAR4 inhibited miR-665 expression and further promoted STAT3 expression, this signaling cascade was essential to colon cancer cells survival, self-renewal and migration." (PMID 30962766, 2019). "However, whether BCAR4 plays a critical role in colon cancer remains to be elaborated." (PMID 29190958, 2017).
lung carcinoma (5 papers, 2019 to 2023). "As the detected fusions of BCAR4 in lung cancer commonly included exon 4 of BCAR4, the effect of a short protein of BCAR4 was compared to CD63–BCAR4 fusion protein." (PMID 33204025, 2021). "We obtained susceptibility genes corresponding to the four serological indexes associated with lung cancer as follows: NSE, LATS1; CA153, BCAR4; CYFRA21-1, YAP; and CA125, PVT1." (PMID 34630106, 2021). "Through literature retrieval and mining technology, we obtained susceptibility genes corresponding to the four serological indexes associated with lung cancer as follows: NSE, LATS1; CA153, BCAR4; CYFRA21-1, YAP; and CA125, PVT1." (PMID 34630106, 2021). "In patients with lung cancer harboring fusion transcripts of BCAR4, no other known activating mutations of EGFR and KRAS genes were found." (PMID 36081848, 2022). "Taken together, these results suggest that EGFR/HER2 inhibitors are potential therapeutic options for BCAR4 fusion-harboring lung cancer patients, even in the absence of EGFR mutations." (PMID 36081848, 2022). "Our findings suggest that dual inhibition of EGFR/HER2 may be a potential treatment option for lung cancer patients harboring oncogenic BCAR4 fusion, even in the absence of EGFR mutations." (PMID 36081848, 2022).
breast tumor (3 papers, 2010 to 2019). "BCAR4 mRNA levels were measured in primary breast tumours, and evaluated for association with progression-free survival (PFS) and clinical benefit in patients with oestrogen receptor (ERα)-positive tumours receiving tamoxifen as first-line monotherapy for advanced disease." (PMID 20859285, 2010). "The levels of BCAR4 mRNAs were determined by quantitative RT–PCR of complementary DNA preparations of primary breast tumours." (PMID 20859285, 2010). "Our cell model suggests that BCAR4-positive breast tumours are driven by ERBB2/ERBB3 signalling." (PMID 20859285, 2010).
esophageal squamous cell carcinoma (3 papers, 2021 to 2023). Esophageal squamous cell carcinoma (ESCC) is a type of esophageal carcinoma (EC) that can affect any part of the esophagus, but is usually located in the upper or middle third. "However, the role of lncRNA BCAR4 in esophageal squamous cell cancer (ESCC) remains unknown." (PMID 33602031, 2021).
glioma (3 papers, 2021 to 2023). A benign or malignant brain and spinal cord tumor that arises from glial cells (astrocytes, oligodendrocytes, ependymal cells). "Upregulated EGFR and its interaction with BCAR4 were proved in glioma cells in their study." (PMID 36081848, 2022).
lung adenocarcinoma (3 papers, 2019 to 2022). A carcinoma that arises from the lung and is characterized by the presence of malignant glandular epithelial cells. "The reason to focus our attention on BCAR4 fusion was based on the discovery of a different fusion variant of BCAR4 that was recently reported in additional patients with lung adenocarcinoma." (PMID 33204025, 2021). "This fusion was noticeable because the recurrent fusions of BCAR4 were reported by recent genomic analyses of lung adenocarcinoma." (PMID 33204025, 2021). "We could observe the recurrent fusions of BCAR4 in a total of four patients with lung adenocarcinoma and demonstrated the oncogenic effect of this novel fusion." (PMID 33204025, 2021). "We also suggest that lung adenocarcinomas harbouring BCAR4 fusions might be a clinically relevant subgroup with a targetable oncogenic driver, among patients without EGFR and KRAS mutations." (PMID 33204025, 2021). "Interestingly, the BCAR4 fusion-positive patients showed the consistent features of being never-smokers, exhibiting absent or rare mutations of EGFR or KRAS genes and diagnosis with lung adenocarcinoma." (PMID 33204025, 2021). "The recurrent fusions of BCAR4 that were identified in lung adenocarcinoma without known drivers made it feasible to infer the oncogenic functions of BCAR4 fusion." (PMID 33204025, 2021). "Therefore, our findings suggest that BCAR4 rearrangements need to be surveyed in lung adenocarcinoma without identifiable driver oncogenes and may serve as a potential therapeutic avenue for the patients." (PMID 33204025, 2021). "Therefore, among the never-smoker lung adenocarcinoma cases without any known driver alterations in oncogenes such as EGFR, KRAS, ALK, etc., the estimated fraction of BCAR4 fusion could be approximately 2.2% (1/44)." (PMID 33204025, 2021).